FAM217B (family with sequence similarity 217 member B)
Synonyms: C20orf177; dJ551D2.5
Tractability: PROTAC: ubiquitination databases record sites on it.
Gene: Protein-coding gene on chromosome 20 (59,933,643 to 59,949,387, forward strand). Ensembl gene ENSG00000196227.
Subcellular location (Human Protein Atlas): Nucleoplasm
Gene Ontology:
Molecular function: protein binding
Cellular component: nucleoplasm
Genetic constraint (gnomAD): Loss-of-function variants: 1 observed, 1.77 expected, observed/expected ratio (o/e) 0.56, 90% interval 0.18 to 1.79. That is too few expected variants to judge how well the gene tolerates losing a copy. Missense variants: 463 observed, 482.87 expected, observed/expected ratio (o/e) 0.96, 90% interval 0.89 to 1.03. Synonymous variants: 163 observed, 181.88 expected, observed/expected ratio (o/e) 0.9, 90% interval 0.79 to 1.02.
Homologues: Orthologues: chimpanzee FAM217B (100% identical), macaque FAM217B (96% identical), guinea pig FAM217B (71% identical), rabbit FAM217B (71% identical), mouse Fam217b (63% identical), pig FAM217B (63% identical), rat Fam217b (62% identical), dog FAM217B (51% identical), zebrafish fam217bb (23% identical), zebrafish fam217ba (13% identical). Paralogues in human: FAM217A (17% identical).